WNT10A (Wnt family member 10A)
Diseases named in the same sentence as WNT10A in open-access papers (continued):
Sharing a sentence is not in itself a finding about the gene and the disease.
Parkinson disease (1 paper, 2024). A progressive degenerative disorder of the central nervous system characterized by loss of dopamine producing neurons in the substantia nigra and the presence of Lewy bodies in the substantia nigra and locus coeruleus. "Wnt10a, which is associated with both Parkinson’s disease and fat accumulation, exhibits a direct correlation with the inflammatory cytokine gene Lin37." (PMID 38396669, 2024).
sarcoidosis (1 paper, 2025). Sarcoidosis is a multisystemic disorder of unknown cause characterized by the formation of immune granulomas in involved organs. "Notably, WNT10A is a key component of the Wnt/β-catenin signaling pathway, which was found to be significantly enriched in both sarcoidosis and LC (FDR-adjusted p = 0.001)." (PMID 40797277, 2025). "Among the twelve common DEGs, SALL4, WNT10A, RASAL1, CAMK2B were significantly upregulated while GADD45B, KLF4, OLR1, CSF3, WIF1, RAMP3 and AGER downregulated in both sarcoidosis and LC as compared to the controls." (PMID 40797277, 2025).
Skin ulcer (1 paper, 2018). A discontinuity of the skin exhibiting complete loss of the epidermis and often portions of the dermis and even subcutaneous fat. "We subjected WT and WNT10A–/–mice to skin ulcer formation in a murine model of wound healing." (PMID 29596490, 2018). "We subjected C57BL/6J wild-type (WT) or WNT10A–/–mice to skin ulcer formation." (PMID 29596490, 2018). "In line with our previous data, after establishing the murine wound healing model, we detected the specific expression of WNT10A in the injured skin ulcer of WT mice by immunohistochemistry, but not in WNT10A–/–mice." (PMID 29596490, 2018).
tumor (42 papers, 2010 to 2025). "Seven hub genes, REG4, S100A7, CLCA1, FABP4, RETNLB, SFRP2, and WNT10A, were all significantly associated with CC patient prognosis and differentially expressed in normal and tumor tissues." (PMID 36941538, 2023). "Ligands of the WNT canonical pathway, such as WNT1 and WNT10A, are associated with tumor progression, poor prognosis, and tumor invasiveness in ccRCC patients by oncogene activation, such as c-Myc and cyclin D1." (PMID 36910160, 2023). "However, to determine associations between FANCD2 and WNT10A germline mutations and clinical manifestation, e.g., response to therapy and prognosis or tumor molecular-level alterations, there is a need for a group of patients harboring variants in the gene." (PMID 39768544, 2024). "To identify the possible mechanisms underlying tumor progression related to circadian rhythms, we set up nude mouse xenograft models and revealed that artificial light stress induced tumor growth and angio/stromagenesis through WNT10A overexpression." (PMID 21203463, 2010). "On the other hand, our data indicate that both endothelial cells and stromal cells may be activated by WNT10A signals from non tumor cells, such as cancer associated fibroblasts." (PMID 21203463, 2010). "To further assess the impact of germinal FANCD2 and WNT10A mutations on the tumor, we conducted WES (whole exome sequencing) for the patient’s tumor sample." (PMID 39768544, 2024). "In order to further prove that NE can regulate the expression level of WNT7A, we detected the expression levels of Wnt1, Wnt2, Wnt3a, Wnt4, Wnt5a, Wnt6, Wnt7a and Wnt10a in tumour tissues of anti-PD-1 mAb + Vehicle and NE + anti-PD-1 mAb + Vehicle groups." (PMID 36646807, 2023). "The study showed that in ICC patients, the Wnt ligands Wnt7b and Wnt10a were highly expressed in tumor tissues." (PMID 36209344, 2022). "Recent studies have indicated that Wnt10a plays an essential role in tumor growth, wound healing, osteogenesis, adipogenesis, and female fertility using Wnt10a-/- mice." (PMID 35884806, 2022). "Of note, WNT10A mRNA was statistically different between tumor and adjacent normal tissue, but its abundance was low in these samples." (PMID 35850748, 2022). "miR-378 family members, especially miR-378a-3p, have been proposed to function as tumor suppressors by suppressing Wnt/β-catenin signaling activation via targeting WNT10a and DVL2." (PMID 34446021, 2021). "Further analysis of the correlation between the WNT gene family and clinicopathological parameters of UCEC showed that the WNT1, WNT3, WNT7A, WNT7B, WNT8B, and WNT10A genes were expressed at significantly different levels at different tumor stages." (PMID 34565373, 2021). "Several studies demonstrated that Wnt10a was highly expressed in CRC tissues and several corresponding cell lines, and a higher Wnt10a expression level was associated with an advanced tumor stage." (PMID 32923386, 2020). "Consistent with previous reports in PDAC organoids, WNT5A, WNT7A, WNT7B, and WNT10A mRNA were highly expressed in PDCLs, suggesting a tumor cell-intrinsic origin for these WNT ligands." (PMID 32402285, 2020). "Expression levels the remaining Wnt ligands, including Wnt1, Wnt3, Wnt4, Wnt5A, Wnt8A, Wnt9B, Wnt10A and Wnt16, remained insignificantly different between liver tumors tissues and adjacent non-tumor tissues." (PMID 30814912, 2019). "Circadian disruption in mouse xenograft models results in tumour progression through Wnt10A-dependent activation of angio- and stromagenesis." (PMID 31014368, 2019).
tumor (continued). "Western blot analysis showed that Wnt3, Wnt3a and Wnt10a were indeed expressed in the tumor grafts, and their expression levels were higher than those in normal subcutaneous tissue and normal mouse colon." (PMID 28147310, 2017). "We previously showed that WNT10A is a novel angio/stromagenic factor involved in such processes as tumor growth, wound healing and tissue fibrosis." (PMID 25054240, 2014). "The results presented in this paper are both interesting and unexpected and strongly suggest that disruption of circadian rhythms promotes tumor growth through WNT10A-dependent angio/stromagenesis resulting from increased levels of oxidative stress." (PMID 21203463, 2010). "Only the tumor stroma stained positive for WNT10A, strongly suggesting expression by stromal cells such as fibroblasts, myofibroblasts, smooth muscle cells, and pericytes." (PMID 21203463, 2010). "WNT10A heterozygous germline variant was present in the tumor sample with VAF 0.15, which corresponded to the loss of the WNT10A pathogenic variant in the tumor sample (as predicted purity is 0.68 and there is LOH in the WNT10A region)." (PMID 39768544, 2024). "In addition, we discovered that cluster 2 is highly associated with some tumor stemness-related transcription factors: WNT5A, WNT10A, GATA2, and FOSL2." (PMID 38339238, 2024). "Additionally, the levels of β-catenin, WNT2B, and WNT10A were elevated in tumor specimens derived from lincROR overexpression group." (PMID 39546475, 2024). "Expression levels of seven CBX7 targets, namely Wnt10a, Ccne1, Fgfr2, Bhlhe22, Klhdc8a, Pde10a, and Dusp4, which had been significantly inhibited in miR-181ab1 KO compared to WT tumours in mice, were also significantly lower in either iClust2 or iClust3 than iClust1 HCCs." (PMID 35867177, 2022). "WNT signaling is also known to play an important role in cancer and stem cell biology, indicating that WNT10A might affect not only the tumor microenvironment, but also stem cells themselves." (PMID 21203463, 2010). "Based on these results, we hypothesized that WNT10A was functioning as a growth factor for both vascular endothelial cells and fibroblasts and was involved in a novel mechanism of tumor growth, possibly via the promotion of angio/stromagenesis." (PMID 21203463, 2010). "On the other hand, WNT10A expression markedly increased in fibroblastic cells in the hyperplastic stroma of keloid tissue, suggesting that WNT10A functions as an angio/stromagenesis gene in tumor progression, thus supporting the “old” hypothesis." (PMID 21203463, 2010). "For instance, the upregulation of WNT10A, RASAL1, CAMK2B, and SALL4 suggests their involvement in tumor-promoting processes, such as cell proliferation, migration, and immune evasion." (PMID 40797277, 2025). "Eight genes exhibited greater than 340-fold increases in expression in tumor tissues (CLDN6, KLK7, WNT10A, MYBL2, MAL2, KRT7, PRSS8, EPCAM; Median (Range) of fold increase = 344 (261–7267))." (PMID 41465326, 2025). "Consistent with low WNT signaling in RevCSCs, BLM tumor stem cells had decreased expression of WNT/stemness-related genes compared to Min tumors such as Axin2, Id2, Sox4, Wnt6, Wnt10a, Id3, Prox1, and Id1." (PMID 38893159, 2024). "Combined expression of WNT ligands (WNT3A, WNT4, WNT7B, WNT9A, WNT10A, WNT11) in BRCA patient tumours has a positive correlation (R = 0.27, p value = 0) with the combined expression of key EMT-inducing transcription factors SNAI1, SNAI2, ZEB1, ZEB2 and TWIST1." (PMID 38678032, 2024). "More importantly, cluster 2 exhibits a strong positive correlation with transcription factors WNT5A, WNT10A, GATA2, and FOSL2, all recognized for their involvement in tumor stemness." (PMID 38339238, 2024). "We found that 3.8% of top down-regulated DEGs in GKO tumours were CBX7 targets, including Wnt10a, CCNE1, FGFR2, and DUSP4." (PMID 35867177, 2022).
tumor (continued). "Conversely, WNT5A, WNT7B, WNT2, WNT7A, WNT10A and WNT3 were tumor-positive WNTs, which significantly increased in many carcinomas." (PMID 35850748, 2022). "Currently TNF, WNT10A, PDGFA, and NRG1 secreted by infiltrated dendritic cells in the tumor microenvironment were identified to be likely involved in the neuropathic pain using RNA-seq, scRNA-seq, and ChIP-seq data." (PMID 32434423, 2020). "The paracrine factors such as TNF, WNT10A, PDGFA, and NRG1 were also elevated in tumor-infiltrating dendritic cells." (PMID 32434423, 2020). "(E) Wnt7b and Wnt10a expression in MEC (n = 3) and MEKO tumor cells (n = 3) is presented as the mean fragments per kilobase of exon model per million mapped fragments (FPKM) ± SEM." (PMID 29856313, 2018). "Knocking-out Wnt5a but not Wnt10a in tumors suppressed the ability of tumor cells to induce Lin28b expression in CAFs, highlighting the role of Wnt5a in Lin28b induction." (PMID 37898598, 2023). "Additionally, the box-and-whiskers plots indicated that WNT10A, PDGFA, and TNF were out of normal distribution due to extremely high expression in many tumor patients which were individually labeled with dots." (PMID 32434423, 2020). "To determine the expression of Wnts in non-CRC cell types in the tumor grafts, we sorted host-derived endothelial cells, fibroblasts, macrophages and dendritic cells and tested mRNA levels of Wnt3, Wnt3a, Wnt5a and Wnt10a in these cells." (PMID 28147310, 2017). "Interestingly, the tumor instead possessed two somatic variants in negative WNT regulators, genes DKK1 and WIF1, while WNT10A damage or knockout was connected with WNT deactivation." (PMID 39768544, 2024). "Moreover, the relevance of ROBO3-dependent STAT3 activation in BL subtype identity and plasticity was supported by decreased expression of the p-STAT3 downstream target WNT10A, a member of the canonical WNT pathway and driver of EMT-related tumor cell invasion." (PMID 35993361, 2022). "The current research identified that infiltrated dendritic cells in the tumor microenvironment could synthesize hormones and secret the paracrine factors such as TNF, WNT10A, PDGFA, and NRG1 which could sensitize sensory neurons to promote neuropathic pain associated with multiple cancers." (PMID 32434423, 2020). "A positive immunohistochemical reaction for WNT10A, Fzd5, β-catenin, GSK-3ß, CacyBP/SIP, and LMP7 was observed in all studied kidneys tissues, although the intensity of immunoreaction varied between non-malignant kidney and RCC tissue samples, depending on the histological type of the tumor." (PMID 33330038, 2020). "Remarkably, for the very first time, we could show that PTSMT are characterized by WNT6/WNT10A regulation while all other tumor entities under investigation showed almost no expression of these two factors." (PMID 29881541, 2018). "Only the tumor stroma stained positive for WNT10A and WNT10A is also highly expressed in keloid dermal fibroblasts but not in normal dermal fibroblasts indicated that WNT10A may be a novel angio/stromagenic growth factor." (PMID 21203463, 2010).
cancer (22 papers, 2010 to 2025). A tumor composed of atypical neoplastic, often pleomorphic cells that invade other tissues. "The Wnt signalling pathway, known for its role in cancer development, is implicated in GC through the upregulation of Wnt10A in gastric mucosa-associated cells, further activating the Wnt-β-catenin-Tcf signalling pathway, significantly contributing to GC development." (PMID 38711123, 2024). "Besides the critical role in the development of ectodermal lineages, increased expression of WNT10A has previously been implicated in a variety of cancers by up-regulation of the β-catenin pathway." (PMID 27881089, 2016). "Cytokines such as TNF, growth factors including PDGFA and NRG1, and others like WNT10A were identified to interact with their receptors on neurons or other cells such as microglial cells to directly or indirectly sensitize neuropathic pain associated with cancers." (PMID 32434423, 2020). "Among the WNT ligands, WNT7A, WNT7B and WNT10A have the highest expression in cancer cells, and the largest increase in expression in bulk PDACs compared to normal pancreatic tissue." (PMID 38678032, 2024). "An up-regulation of the components of WNT/β-catenin, in particular of WNT10a and WNT10b, along with change in the expression pattern of β-catenin has been documented in cancer patients." (PMID 37628609, 2023). "Interestingly, mutations in the AXIN2, MSX1, PAX9, and WNT10A genes may be associated with cancers." (PMID 34378652, 2021). "FZD8, plasminogen activator, urokinase receptor, ITGA2, WNT2B, TIMP3, WNT5B, FGF5, heparanase, HBEGF and WNT3A were up-regulated in the proteoglycan pathways in cancer, whereas WNT10A, PIK3R3, IGF2 were down-regulated." (PMID 30482199, 2018). "In addition, Wnt10a, one of the 19 known Wnt ligands, has been shown in many studies to participate in cancer cell proliferation and invasion through activating Wnt/β‐catenin signalling." (PMID 38528645, 2024). "As RGL1 and WNT10A are widely expressed in both normal and cancer tissues, determining the immunogenic epitopes that autoantibodies target could lend insight into the interactions of the immune system and tumorigenesis." (PMID 37444527, 2023). "Taken together, this is consistent with the fact that patients with structural WNT10A mutations are not reported to have increased risk for cancer." (PMID 27881089, 2016). "WNT10A overexpression has been observed in some cancer cell lines, but its role in RCC is still unknown." (PMID 23094073, 2012). "Because an old hypothesis suggests that cancer results from uncontrolled wound-healing, we investigated WNT10A expression in keloid tissue." (PMID 21203463, 2010). "This cancer cell subpopulation also showed statistically significant elevated expression of WNT7B, WNT7A, WNT10A and WNT4 besides the CSC markers, compared to the rest of the PDAC cells." (PMID 38678032, 2024). "Conversely, the cancer cell–derived WNT7A, WNT7B, and WNT10A and stromal WNT3 and WNT9A were highly expressed in the squamous subtype." (PMID 35536676, 2022). "Consistently, we detected increased mRNA expression of WNT7B (P = 0.0003), as well as WNT10A (P = 0.0023) and WNT5A (P = 0.088), in most cancer samples." (PMID 35850748, 2022). "Our data annotated 17 WNTs and found that WNT2B, WNT10A, WNT5A and WNT7B showed a similar cancer-positive pattern, and WNT7B was the most significant one." (PMID 35850748, 2022). "We propose that cancer stem cells use autocrine mechanisms to upregulate WNT signaling, as shown by the higher secretion of WNT10A and by the fact that NOTCH signaling is activated downstream of WNT." (PMID 32066735, 2020). "Because β-catenin signaling is involved in several pathways of cancer aggressiveness, we also performed some functional assays in RCC cell line model to investigate the oncogenic role of WNT10A." (PMID 23094073, 2012). "They identified several genes (AXIN2, MSX1, PAX9, WNT10A, EDA, BARX, and BRCA1) that may play a role in both hypodontia and cancer development." (PMID 38523193, 2024).
cancer (continued). "D’Agostino and Pearson omnibus normality test indicated that the expression of WNT10A, TNF, and PDGFA in various cancers did not normally distribute." (PMID 32434423, 2020).
adenocarcinoma (1 paper, 2022). A common cancer characterized by the presence of malignant glandular cells. "WNT7A and WNT10A may contribute to female reproductive system adenocarcinomas, while LRP5 prefer adenocarcinomas of digestive organs." (PMID 35850748, 2022).
infection (1 paper, 2019). The state of being infected such as from the introduction of a foreign agent such as serum, vaccine, antigenic substance or organism. "The level of the epigenetic marker at the position of genes WNT10A, JUNB, FOSL2, TNFAIP3, KLF4 and EDN1 was increased, and decreased at the position of genes MYCN and PCSK9, as was demonstrated by using the in vitro HCV-infection systems." (PMID 31216276, 2019).
proliferative retinopathy (1 paper, 2024). "WNT10A has been implicated in pathological vascular growth in proliferative retinopathy and has also been observed to be upregulated during rod degeneration, activating Wnt signaling and thus protecting PRs from oxidative stress." (PMID 38994994, 2024).
WNT10A also shares sentences with these, for which no sentence is quoted: Hypodontia (12 papers); hypohidrotic ectodermal dysplasia (7); Hyperhidrosis (4); idiopathic pulmonary fibrosis (3); onychodysplasia (3); esophageal cancer (2); Palmoplantar hyperkeratosis (2); renal fibrosis (2); taurodontism (2); tricho-dento-osseous syndrome (2); adenoma (1); Alopecia universalis (1); basal cell tumours (1); brittle cornea syndrome (1); Carvajal syndrome (1); cervical cancer (1); cholestasis (1); COVID-19 (1); cystic fibrosis (1); dental caries (1); diabetes (1); diffuse large B-cell lymphoma (1); eczema (1); epidermolysis bullosa (1); Erythema (1); esophageal squamous cell carcinoma (1); genetic disorder (1); head and neck cancer (1); hidrocystoma (1); hyperplasia (1).
A further 28 diseases each share a sentence with WNT10A in 1 paper.